RNU2-17P (RNA, U2 small nuclear 17, pseudogene)
Gene: Small nuclear RNA gene on chromosome 1 (150,236,967 to 150,237,156, forward strand). Ensembl gene ENSG00000222222.
Homologues: Orthologues: chimpanzee U2 (100% identical), macaque U2 (95% identical), tropical clawed frog U2 (65% identical), rabbit U2 (65% identical), dog U2 (64% identical), guinea pig U2 (59% identical), rabbit U2 (30% identical). Paralogues in human: U2 (91% identical), RNU2-3P (87% identical), RNU2-2 (86% identical), U2 (86% identical), RNU2-4P (85% identical), RNU2-52P (82% identical), RNU2-26P (82% identical), RNU2-59P (82% identical), RNU2-25P (81% identical), RNU2-48P (81% identical), RNU2-57P (81% identical), RNU2-64P (81% identical), and 65 more.